IKBKB (inhibitor of nuclear factor kappa B kinase subunit beta)
Diseases named in the same sentence as IKBKB in open-access papers (continued):
Sharing a sentence is not in itself a finding about the gene and the disease.
Alzheimer disease (6 papers, 2017 to 2024). A progressive, neurodegenerative disease characterized by loss of function and death of nerve cells in several areas of the brain leading to loss of cognitive function such as memory and language. "IKBKB can alleviate the neuron injury in Alzheimer’s Disease via regulating autophagy and RIPK1-Mediated necroptosis." (PMID 38020922, 2023).
breast tumor (6 papers, 2008 to 2022). "Furthermore, there are 7 literature support of genes MUC1 and HNF3-alpha related to breast neoplasm compared to 6 (MUC1) for EGFR and none for IKBKB." (PMID 18254968, 2008).
combined immunodeficiency (5 papers, 2020 to 2025). A broad classification of inherited disorders presenting at birth that affect both the cell-mediated and humoral aspects of the immune response. "Some studies have shown that inhibitor of kappa light polypeptide gene enhancer in B‐cells, kinase beta (IKBKB), which is upregulated in the cancer pathway, causes human combined immunodeficiency." (PMID 35334492, 2022). "IKBKB deficiency is a rare immunophenotype characterized by severe combined immunodeficiency (SCID), usually evident in neonates with persistent respiratory or gastrointestinal infections caused by viruses, bacteria, or fungi, often associated with prolonged diarrhea and failure to thrive." (PMID 40124362, 2025). "PV in the IKBKB gene can result in severe or milder forms of combined immunodeficiency." (PMID 40124362, 2025).
COVID-19 (5 papers, 2020 to 2024). A disease caused by infection with severe acute respiratory syndrome coronavirus 2. "Based on the binding energy score, IKBKB was identified as a key target of Scutellariae radix for the treatment of COVID-19 through anti-inflammatory effects." (PMID 36186074, 2022).
inflammatory bowel disease (5 papers, 2010 to 2025). A spectrum of small and large bowel inflammatory diseases of unknown etiology. "Several IEC signature TFs have known associations with human Inflammatory Bowel Diseases (IBD), including SMAD7, CEBPG, STAT3, XBP1, HNF4A, ELF3, IRF1, and NFκB components IKBKB, IKBKG, and NFKBIZ." (PMID 28850571, 2017).
skin cancer (5 papers, 2013 to 2024). "The absence of p16 and p19, leading to an increase in IKBKB expression, favors the appearance of a highly aggressive kind of skin cancer." (PMID 39337357, 2024).
acute myeloid leukemia (4 papers, 2016 to 2022). Acute myeloid leukemia (AML) is a group of neoplasms arising from precursor cells committed to the myeloid cell-line differentiation. "Two of the 23 MM essential genes, PIM2 and IKBKB, are catalogued as targets for six therapies across 19 disease categories: nine in the context of cancer including MM, non-Hodgkin lymphoma, and acute myeloid leukaemia." (PMID 35882937, 2022). "The genes contributing the most to the acute myeloid leukemia pathway (RAF1, RELA, and IKBKB) are related with NF-KB signaling, a process already known to also play a role in AD and PD." (PMID 33362460, 2020).
bladder cancer (4 papers, 2020 to 2025). "The extensively amplified hot zones on the p of chromosome 8 may be associated with FGFR1 and IKBKB, which are often deregulated by amplification in lung, colon, and bladder cancers." (PMID 34054918, 2021). "Male-specific hub genes, including DAXX, IKBKB, PDGFRA, and PPARG, showed significant correlations with immune cell types, highlighting a distinct immune microenvironment in male bladder cancer." (PMID 40458476, 2025).
depression (4 papers, 2019 to 2022). "Nevertheless, our findings confirm at least a partial association between TGFA, TGFB, PTGS2, IRF1 and IKBKB genes and depression, and hence it is highly likely that inflammation plays a role in psychiatric disorders." (PMID 33946816, 2021). "Summarizing, our results confirm at least a partial association between TGFA, TGFB, IRF1, PTGS2 and IKBKB and depressive disorders." (PMID 33946816, 2021). "Distribution of genotypes and alleles of rs1800469 (TGFB1), rs2070729 (IRF1), rs5275 (PTGS2), rs4648308 (PTGS2), rs2166975 (TGFA), rs5029748 (IKBKB) and the risk of depression occurrence." (PMID 32140313, 2020). "Distribution of genotypes and alleles of rs2070729 (IRF1), rs5275 (PTGS2), rs4648308 (PTGS2), rs2166975 (TGFA), rs5029748 (IKBKB) and the risk of depression occurrence in male and female population." (PMID 32140313, 2020). "The trend of increasing risk of depression prevalence is also present in the case of linked genotypes of rs5029748—IKBKB and rs4648308—PTGS2." (PMID 32140313, 2020). "Gene-gene interactions of rs1800469 (TGFB1), rs2070729 (IRF1), rs5275 (PTGS2), rs4648308 (PTGS2), rs2166975 (TGFA), rs5029748 (IKBKB) and the risk of depression occurrence." (PMID 32140313, 2020). "We observed that A/G of the rs2166975 TGFA, A/C of rs2070729 IRF1 and G/T of rs5029748 IKBKB were associated with an increased risk of depression development while the T/T of rs5029748 IKBKB, T/T of rs4648308 PTGS2 and G/G of rs2166975 TGFA reduced this risk." (PMID 32140313, 2020). "Concluding, our results indicate that TGFA, TGFB, PTGS2, IRF1 and IKBKB could be associated with depression and its treatment." (PMID 36012250, 2022). "Therefore, defective expression of NF-kB as the pro-inflammatory transcription factor, caused by alterations in IKBKB gene, may play a role in the development of depression." (PMID 32140313, 2020). "The present study is the first to investigate the levels of TGFA, IRF1 and IKBKB mRNAs in an animal model of depression." (PMID 33946816, 2021). "Adverse effect associations between drugs and diseases are also found in the top-ranking predictions, such as the triplet association among Arsenic trioxide, inhibitor of nuclear factor kappa-B kinase subunit beta (IKBKB) and major depressive disorder." (PMID 31839008, 2019). "Our key findings reveal that TGFA, TGFB, PTGS2, IRF1 and IKBKB could be responsible for immune system activation in depression." (PMID 36012250, 2022). "Moreover A/G-G/T genotype of rs5029748 IKBKB and rs2166975—TGFA, increased risk of depression but G/T-T/T are associated with lower risk of disease." (PMID 32140313, 2020). "Therefore, alterations in IKBKB gene expression can disrupt the NF-kB system and may influence developing depression." (PMID 33946816, 2021). "This study focuses on the contribution of genes such as IRF1, PTGS2, IKBKB, TGFA and TGFB in the molecular basis of depression as well as the impact of chronic agomelatine administration." (PMID 36012250, 2022).
systemic lupus erythematosus (4 papers, 2012 to 2023). An autoimmune multi-organ disease typically associated with vasculopathy and autoantibody production. "A previous large-scale replication study validation of a genome wide association study (GWAS) identified IκB kinase β (IKBKB) single nucleotide polymorphisms (SNPs) as a risk factor associated with systemic lupus erythematosus (SLE) in a Chinese Han population." (PMID 26167925, 2015).
acne (3 papers, 2024 to 2025). An inflammatory process of the sebaceous glands which is characterized by comedones, nodules, papules and/or pustules on the skin. "The expression of CXCL10, MMP9, IL1B, CXCL8, and CXCR4 were co-regulated by IRF1, STAT1, STAT3, IKBKB, HDAC1, ETS1, and CEBPB, which were highly expressed in rosacea and acne lesions." (PMID 38321132, 2024).
colon adenocarcinoma (3 papers, 2014 to 2024). "Conversely, in esophageal adenocarcinoma, reduced IKBKG expression is linked to longer overall survival, while higher IKBKB expression in colon adenocarcinoma is associated with longer overall survival." (PMID 39337357, 2024).
Hydrocephalus (3 papers, 2017 to 2025). Hydrocephalus is an active distension of the ventricular system of the brain resulting from inadequate passage of CSF from its point of production within the cerebral ventricles to its point of absorption into the systemic circulation. "Astrocyte-specific activation of the NF-κB pathway, via the constitutively active inhibitor of nuclear factor kappa-B kinase subunit beta (IKK2), also known as IKK2-CA for the constitutively active form), has been shown to cause postnatal hydrocephalus in mice." (PMID 40722587, 2025).
lymph node metastasis (3 papers, 2016 to 2024). "The expression levels of miR-16 were negatively associated with T stages, whereas the expression of IKBKB was positively correlated with T stages, lymph node metastasis and clinical stages." (PMID 26993770, 2016). "We then analyzed miR-16 and IKBKB expression and their possible associations with clinicopathological parameters, such as age, pathological classification, pathological grade, tumor size (T staging), lymph node metastasis (N staging), distant tumor metastasis (M staging) and clinical staging." (PMID 26993770, 2016).
oral squamous cell carcinoma (3 papers, 2020 to 2023). "miR-199a 5p was found to function as a tumor suppressor in oral squamous cell carcinoma via targeting the inhibitor of nuclear factor kappa-B kinase subunit beta (IKKβ)/NF-κB signaling pathway, which is quite interesting as IKKβ/NF-κB has generally been reported to promote tumorigenesis." (PMID 33806361, 2021).
pancreatic ductal adenocarcinoma (3 papers, 2023 to 2025). An infiltrating adenocarcinoma that arises from the epithelial cells of the pancreas. "At the same time, the deletion of IKBKB reduces the risk of pancreatic ductal adenocarcinoma and causes less severe pancreatic lesions." (PMID 39061149, 2024).
Salmonella Infections (3 papers, 2018 to 2024). Infections with bacteria of the genus SALMONELLA. "The signalling adapter molecule IKBKB was significantly upregulated in Kashmir favorella after Salmonella infection that showed its influence on FOXO3 expression as well." (PMID 37098463, 2023).
esophageal carcinoma (2 papers, 2019 to 2024). A primary or metastatic malignant neoplasm involving the esophagus. "Our findings reveal that IKBKB and IKBKG are significantly upregulated in all examined cancers, while CHUK is upregulated in esophageal carcinoma and stomach adenocarcinoma." (PMID 39337357, 2024).
esophageal squamous cell carcinoma (2 papers, 2019 to 2024). Esophageal squamous cell carcinoma (ESCC) is a type of esophageal carcinoma (EC) that can affect any part of the esophagus, but is usually located in the upper or middle third. "Downregulated IKBKB gene expression was correlated with shorter OS (p = 0.015) in the esophageal squamous cell carcinoma subtype of ESCA." (PMID 39337357, 2024). "Lower expression levels of CHUK, IKBKB, and IKBKG in stomach adenocarcinoma and IKBKB in esophageal squamous cell carcinoma correlate with shorter overall survival." (PMID 39337357, 2024).
gastric adenocarcinoma (2 papers, 2015 to 2024). "For instance, in stomach adenocarcinoma, CHUK and IKBKB are upregulated in higher histological grades and greater lymph node infiltration." (PMID 39337357, 2024).
HIV-1 infection (2 papers, 2024 to 2025). The type species of lentivirus and the etiologic agent of acquired immunodeficiency syndrome (AIDS). "In the gene-pathway connections, multiple molecules and kinases for NF-κB signaling (e.g., IKBKB, JUN, FOS, MAP2K2, NFKBIA, TLR4) connected the HIV-1 infection and other inflammatory or anti-viral pathways." (PMID 39283947, 2024).
Huntington disease (2 papers, 2023 to 2024). Huntington disease (HD) is a rare neurodegenerative disorder of the central nervous system characterized by unwanted choreatic movements, behavioral and psychiatric disturbances and dementia. "The paucity of mechanistic information on IKK pathways, together with the lack of sensitive methods to quantify endogenous huntingtin phosphorylation, prevented detailed study of the role of IKBKB in Huntington’s disease." (PMID 37553253, 2023).
metastatic tumors (2 papers, 2021 to 2022). "The quantitative real-time PCR (qRT-PCR) showed that circIKBKB-ASO treatment significantly reduced expression of circIKBKB, but not IKBKB mRNA, in bone-metastatic tumors." (PMID 34325714, 2021).
nasopharyngeal carcinoma (2 papers, 2019 to 2022). A carcinoma arising from the nasopharyngeal epithelium. "Differentiation of nasopharyngeal carcinoma cells was induced via inhibiting an epigenetic mechanism by which EZH2 (enhancer of zeste 2 polycomb repressive complex 2 subunit) represses IKKα (inhibitor of nuclear factor kappa-B kinase subunit beta) expression and impairs tumor cell differentiation." (PMID 31661894, 2019).
osteoporosis (2 papers, 2021 to 2023). A condition of reduced bone mass, with decreased cortical thickness and a decrease in the number and size of the trabeculae of cancellous bone (but normal chemical composition), resulting in increased fracture incidence. "Furthermore, bioinformatics analysis revealed that RELA, NFKBIA, and IKBKB, which all belong to the NF-κB family, were hub genes shared between ICA-targeted genes and osteoporosis." (PMID 34803690, 2021).
Pituitary Adenomas (2 papers, 2024). "This study investigated the relationship between specific gene polymorphisms (TRAF2, TAB2, IKBKB) and protein levels and pituitary adenomas (PAs)." (PMID 39061149, 2024). "This study investigated the association of TRAF2 rs867186, TAB2 rs237025, and IKBKB rs13278372 polymorphisms with pituitary adenoma (PA) in a case–control study involving 459 subjects (139 PA patients and 320 controls)." (PMID 39061149, 2024).
primary immunodeficiencies (2 papers, 2014 to 2025). "An example of how better understanding a primary immunodeficiency within a community can help inform public health policies is again illustrated with IKBKB deficiency in the two described Northern Cree communities of Manitoba." (PMID 40061245, 2025). "IKBKB was the most frequent single primary immunodeficiency reported in 18 FN children, mostly from Manitoba, but also from Saskatchewan and Alberta." (PMID 40061245, 2025).
prostate tumors (2 papers, 2015 to 2017). "It is intriguing that some tumors show loss of one single IKBKB allele, in special liver and prostate tumors (40% of the tumors) and head and neck SCCs (35%), which seems to indicate a tumor suppressive role of IKKβ in these cancer types." (PMID 29292732, 2017). "Gene fusions involving IKBKB have also been found, although this process does not seem to be a common mechanism of activation of the gene, as at the moment only a few have been found in breast and prostate tumors." (PMID 29292732, 2017).
rectal cancer (2 papers, 2010 to 2022). A primary or metastatic malignant neoplasm that affects the rectum. "In rectal cancer, only two-locus composite genotypes across IKBKB and NFKB1, and IL6 and NFKB1 markers met significance thresholds." (PMID 21129206, 2010). "Our findings suggest that polymorphisms in IKBKB, IL6, and NFKB1 may jointly interact to influence colon and rectal cancer risk through an inflammation-related pathway." (PMID 21129206, 2010). "In conclusion, hapConstructor provided a useful tool to systematically and comprehensively guide our exploration of multilocus SNP combinations in three candidate inflammation-related genes, IKBKB, IL6, and NFKB1 in a U.S. case-control study of colon and rectal cancer." (PMID 21129206, 2010).
renal carcinoma (2 papers, 2017 to 2023). A carcinoma arising from the epithelium of the renal parenchyma or the renal pelvis. "Subsequently, using the HPA database, we downloaded immunohistochemical images of IKBKG and IKBKB from normal and cancerous tissues and found that their expression of IKBKG and IKBKB in renal cancer tissues was higher than that in normal kidney tissues." (PMID 37847185, 2023).
acquired immune deficiency (1 paper, 2019). "A recent clinical study showed that heterozygous mutation of IKBKB, which encodes IKK2, led to combined T and B lymphocyte deficiency in patients with acquired immune deficiency." (PMID 31040851, 2019).
aging (1 paper, 2024). A developmental process that is a deterioration and loss of function over time. "Within the context of skin aging and various aging-related processes, the immune response-related genes IKBKB and NFKB2, which are integral to the NF-κB signaling pathway, play a pivotal role." (PMID 38263133, 2024).
breast adenocarcinoma (1 paper, 2025). "Mutations in the NOD1/2 signaling pathway and in DNA binding transcription factor activity, affecting genes such as MAP3K7, UBE2N, IKBKG, CHUK, and IKBKB, occurred late in breast adenocarcinoma and ovarian adenocarcinoma." (PMID 39868264, 2025).
chronic granulomatous disease (1 paper, 2025). Chronic granulomatous disease (CGD) is a rare primary immunodeficiency, mainly affecting phagocytes, which is characterized by an increased susceptibility to severe and recurrent bacterial and fungal infections, along with the development of granulomas. "IKBKB deficiency, adenosine-deaminase severe combined immune deficiency (SCID), and chronic granulomatous disease were the most common IEI." (PMID 40061245, 2025).
chronic lymphocytic leukemia (1 paper, 2022). "A similar oncogenic role for miR-708 has been observed in chronic lymphocytic leukemia, where its reduced expression affects NF-κB activity via the kinase-β/IKBKB (IKKβ) targeting." (PMID 35011736, 2022).
epilepsy (1 paper, 2024). A brain disorder characterized by episodes of abnormally increased neuronal discharge resulting in transient episodes of sensory or motor neurological dysfunction, or psychic dysfunction. "IKBKB was also highly expressed in the epilepsy group, while IKBKG was higher only in the T. gondii‐positive groups." (PMID 39046369, 2024).
leiomyoma (1 paper, 2014). A well-circumscribed benign smooth muscle neoplasm characterized by the presence of spindle cells with cigar-shaped nuclei, interlacing fascicles, and a whorled pattern. "Further insight into regulatory function of NF-kB signaling pathway in leiomyoma revealed that the level of phosphorylated IKBKB at Ser-177/181 was elevated and displayed an inverse relationship with miR-200c as compared to myometrium." (PMID 24755559, 2014). "In summary, we showed that leiomyoma express an elevated level of phosphorylated IKBKB at Ser-177/181 as compared to myometrium and using isolated MSMC and LSMC as an in vitro model provided further evidence for the regulatory function of miR-200c on IKBKB and caspase 3/7 activity." (PMID 24755559, 2014). "Although our in vitro data clearly identified IKBKB as a direct target of miR-200c in LSMC, regulatory function of other miRNAs or other gene products may also target IKBKB in leiomyoma." (PMID 24755559, 2014). "As such, an elevated level of IKBKB phosphorylation and lower miR-200c expression in leiomyoma could promote an environment necessary for activation of NF-kB signaling pathway and regulation of specific target genes." (PMID 24755559, 2014). "Our results indicated that gain-of function or knockdown of miR-200c in leiomyoma smooth muscle cells (LSMC) regulated IL8 mRNA and protein expression through direct targeting of IKBKB and alteration of NF-kB activity." (PMID 24755559, 2014).
marginal zone lymphoma (1 paper, 2017). A usually indolent mature B-cell lymphoma, arising from the marginal zone of lymphoid tissues. "IKBKB was recognized as a cancer gene by COSMIC based on the finding of IKBKB activating mutations in Lys175 in around 8% of splenic marginal zone lymphomas of B cells; this mutation renders a constitutively active IKKβ protein." (PMID 29292732, 2017).
mucositis (1 paper, 2024). Mucositis is inflammation and damage of the mucous membranes lining the mouth and other parts of the gastrointestinal (GI) tract. "The κB kinase inhibitor gene IKBKB rs12676482 was related to grade 3–4 radiation-induced acute myelosuppression, but not to mucositis." (PMID 38473311, 2024).